PDE4B (phosphodiesterase 4B)
Diseases named in the same sentence as PDE4B in open-access papers (continued):
Sharing a sentence is not in itself a finding about the gene and the disease.
myopia (3 papers, 2021 to 2024). "Researchers suggest that PDE4B may be a novel high myopia susceptibility gene and play an important role in the development of myopia." (PMID 38660258, 2024). "Furthermore, they agree with our previous conclusion that loss or inhibition of PDE4B leads to rises in cAMP accumulation that are accompanied by declines in collagen type I expression levels and increases in myopia development." (PMID 35116054, 2021). "Taken together with our previous report that loss and inhibition of PDE4B can induce myopia in mice and guinea pigs, PDE4B may be a novel HM susceptibility gene, which may serve as a target for improving therapeutic management of myopia." (PMID 35116054, 2021). "More studies are needed to determine if there is a correlation between PDE4B and high myopia in other larger sample sized cohorts." (PMID 35116054, 2021). "As we previously reported, Pde4b-KO mice exhibit myopia phenotypes, which further supports our contention that it has a HM susceptibility role." (PMID 35116054, 2021). "Drawing upon Zhao’s research, it was observed that reductions in PDE4B and PDE8B levels—enzymes responsible for the catabolic breakdown of cyclic AMP (cAMP)—are associated with the progression of myopia, presumably through the elevation of scleral cAMP concentrations." (PMID 38605967, 2024). "This correspondence between the declines in rs10889602 of the PDE4B gene, PDE4B knockdown, and COL1A1 protein expression levels suggest that PDE4B may be a novel high myopia susceptibility gene, which regulates myopia progression through controlling scleral collagen I expression levels." (PMID 35116054, 2021).
post-traumatic stress disorder (3 papers, 2020 to 2025). An anxiety disorder precipitated by an experience of intense fear or horror while exposed to a traumatic (especially life-threatening) event. "In a GWAS of post-traumatic stress disorder (PTSD) and other stress-related diagnoses, PDE4B was the only GWS risk locus identified." (PMID 39256048, 2024). "Potentially, the treatment with specific PDE4B inhibitors could provide therapeutic relief for patients with persistent fear memories and post-traumatic stress disorders through the alteration of PDE4B activity." (PMID 32438615, 2020).
psoriatic arthritis (3 papers, 2022 to 2024). Joint inflammation associated with psoriasis. "Interestingly, all PDE4 isoforms are expressed in skin lesions of psoriatic arthritis, atopic dermatitis, and discoid lupus erythematosus, with PDE4B and PDE4D being the most prominent in normal dermal fibroblasts." (PMID 39223490, 2024).
allergic asthma (2 papers, 2017 to 2022). A asthma with a basis in a pathological type I hypersensitivity reaction. "In an allergic asthma model, PDE4B ablation impairs allergen-specific T-cell proliferation and Th2 cell functions as well as protects the animal from allergen-induced airway hyperresponsiveness." (PMID 28383060, 2017). "We conclude that PDE4B is a homeostatic regulator of cellular cAMP concentrations in DCs and may be a target for treating Th2-allergic asthma and other settings with low cellular cAMP concentrations." (PMID 35387344, 2022).
Arrhythmia (2 papers, 2024 to 2025). Any cardiac rhythm other than the normal sinus rhythm. "Collectively, our data suggest that PDE4B can physically associate with and predominantly regulates cAMP levels in the RyR2 microdomain, as well as arrhythmia susceptibility upon prolonged catecholamine exposure." (PMID 38534320, 2024). "In both systems, the effects of PDE4B ablation on arrhythmia susceptibility could also potentially originate from both altered regulation of the LTCC complex and from direct effect on the local cAMP levels at and the leakiness of RyR2." (PMID 38534320, 2024). "We could verify the direct impact of PDE4B and PDE4D deficiency on arrhythmia susceptibility by performing analysis of extra beats measurements of single CMs as well as by measuring arrhythmia occurrence in intact Langendorff perfused hearts, either at basal level or upon β-AR stimulation." (PMID 38534320, 2024). "Here, we could detect a strong increase in ventricular tachycardia in PDE4B-KO hearts under ISO stimulation, as opposed to unchanged number of arrhythmias in PDE4D-KO hearts, at least under this stimulation protocol." (PMID 38534320, 2024).
cardiac hypertrophy (2 papers, 2018 to 2023). "The role of PDE4B in the protection against arrhythmia is consistent with the observation of decreased PDE4B activity in cardiac hypertrophy." (PMID 29385021, 2018).
cognitive decline (2 papers, 2021 to 2024). "Long-term inhibition of PDE4B spanning the time window that has been verified to heavily feature synaptic loss has positive effects on cognitive decline and synapse loss later in life." (PMID 38920631, 2024). "This study aimed to investigate whether long-term inhibition of PDE4B by A33 (3 mg/kg/day) can prevent synapse loss and its associated cognitive decline in APPswe/PS1dE9 mice." (PMID 38920631, 2024). "Female monoallelic APPswe/PS1dE9 mice and WT littermates were injected daily with a PDE4B inhibitor, A33 (3 mg/kg), from postnatal 1–4 months, which is the time window that high levels of synapse loss are observed but before cognitive decline is to be expected (7–8 months)." (PMID 38920631, 2024). "Reduced expression of PDE4B post-fight may be associated with protective mechanisms against cognitive decline in TBI55." (PMID 33854105, 2021).
colonic adenoma (2 papers, 2018 to 2024). "Beyond its effect on the number of DSS-induced colonic adenomas, we observed that the loss of PDE4B function has a severe effect on the survival of DSS-treated ApcMin/+ mutant mice." (PMID 30188895, 2018). "Loss of PDE4B function in the ApcMin/+ mouse leads to a significant increase in the number of colonic adenomas." (PMID 30188895, 2018). "Contrary to the hypothesis that PDE4B function is pro-tumorigenic, we observed that ApcMin/+ animals carrying an inactivating mutation in Pde4b developed 1.4-fold more colonic adenomas in the mutant heterozygote and 1.8-fold more in the homozygote." (PMID 30188895, 2018). "The average numbers (± standard deviation) of colonic adenomas are 2.4 ± 2.2 for the Pde4b+/+, 3.3 ± 2.9 for Pde4b-/+, and 4.3 ± 4.6 for the Pde4b-/- genotype." (PMID 30188895, 2018). "The observation that Pde4b affects the colonic adenoma phenotype of ApcMin/+ animals leads to its formal designation as a Modifier of Min (Mom) gene–one whose mutant phenotype depends also on the ApcMin/+ genotype." (PMID 30188895, 2018). "We have found that Pde4b transcript levels are not only enhanced 3.2-fold in colonic adenomas, but also 2.1-fold in the normal colonic epithelium adjacent to tumors." (PMID 30188895, 2018). "Pde4b is one of the triply conserved transcripts whose level is enhanced both in the colonic adenoma and in the normal colonic epithelium, especially adjacent to adenomas." (PMID 30188895, 2018). "It then seems paradoxical that the levels of the Pde4b transcript are enhanced in colonic adenomas." (PMID 30188895, 2018).
diabetes (2 papers, 2015 to 2021). "Among the potential targets of miR-34c-5p, some of the diabetes-related signature genes identified earlier were found, i.e. PTGS2, PDE4B and EMP1 were predicted as targets of miR-34c-5p in three to five algorithms." (PMID 26083362, 2015).
endotoxemia (2 papers, 2020 to 2021). "The inhibition of PDE7A seems to display an additional anti-inflammatory effect, as a strong inhibitor of PDE7A – GRMS-55 demonstrated ~5.5 and ~4.0 times lower IC50 values in LPS-induced endotoxemia and CIA, respectively, than (±)-LSF, which is only a ~2.0 times weaker PDE4B inhibitor than GRMS-55." (PMID 31899535, 2020). "We demonstrated that PDE4B but not PDE4D blockage is essential to obtain a therapeutic effect in animal models of immune-mediated hepatitis, autoimmune rheumatoid arthritis, and endotoxemia." (PMID 31899535, 2020).
fibrosis (2 papers, 2023 to 2025). the formation of excess fibrous connective tissue in an organ or tissue in a reparative or reactive process. "We also found that delayed treatment with several different PDE4 inhibitors reduced the severity of fibrosis in this same model, and a recent phase 3 clinical trial with BI 1015550, a preferential inhibitor of the PDE4B subtype, reduced the rate of lung function decline in patients with IPF48." (PMID 40894033, 2025).
Hepatitis (2 papers, 2020 to 2021). Inflammation of the liver. "Taken together, these results suggest that simultaneous inhibition of both PDE7A and PDE4B induced anti-inflammatory effects in ConA-induced hepatitis by inhibiting the production of pro-inflammatory mediators." (PMID 33919375, 2021). "Thus, it can be concluded that the observed effects of PDE inhibitors in ConA-induced hepatitis arise both from the inhibition of PDE4B and PDE7A." (PMID 31899535, 2020). "The results presented in this paper indicate that due to the balanced anti-inflammatory properties, resulting mainly from PDE7A and, to a lesser extent, PDE4B inhibition, GRMS-55 exhibited high hepatoprotective activity in mice with ConA-induced hepatitis." (PMID 33919375, 2021).
injury (2 papers, 2017 to 2021). Damage inflicted on the body as the direct or indirect result of an external force, with or without disruption of structural continuity. "The genes that were found to downregulate the most during a fight were ADRB2, HRH1, ANXA1 and PDE4B, with the first two upregulated at baseline for pre-fight samples when compared to control data and the latter two with pre-fight gene expression similar to non-head trauma controls." (PMID 33854105, 2021).
ischemic stroke (2 papers, 2017 to 2021). A stroke disorder caused by obstruction of blood flow to the brain, due to thrombotic (local blood clot formation) or embolic (due to a blood clot or other material traveling from another site) event. "This contributes to the rationale of researching more specific PDE4B inhibition as a strategy to reduce emetic side effects in an ischemic stroke experimental model." (PMID 34206420, 2021). "Considering these similarities, PDE4B inhibition might also exert a similar effect following ischemic stroke since neutrophils and microglia are important players of the innate immune activation following stroke." (PMID 34206420, 2021).
nicotine dependence (2 papers, 2022 to 2023). Physical and psychological dependence on nicotine. "PDE4b, a target of apremilast, has been associated with both alcohol and nicotine dependence." (PMID 36656645, 2023). "For cannabis use disorder, 2 genes were significantly associated including, PDE4B (P = 2.09 × 10−6) and FOXP2 (P = 9.30 × 10−7), and one gene for nicotine dependence—ARHGAP22 (P = 2.42 × 10−6)." (PMID 36151087, 2022).
Obesity (2 papers, 2014 to 2021). Accumulation of substantial excess body fat. "PDE4B has been associated with backfat thickness in pigs and with obesity in humans." (PMID 25359100, 2014). "It has been reported that PDE4B is a potential therapeutic target to treat obesity-related metabolic diseases." (PMID 35046895, 2021).
panic disorder (2 papers, 2019 to 2021). An anxiety disorder characterized by multiple unexpected panic attacks with persistent concern of recurring attacks. "The implication of the PDE4B gene in behavior and mood is also supported by the association of PDE4B gene polymorphisms with protection from panic disorder in Russians subjects." (PMID 33414502, 2021). "We evaluated the role of 3 SNPs in the PDE4B gene in the development of panic disorder and found two protective complex genotypes associated with panic disorder." (PMID 31663033, 2019). "The frequencies of alleles of the studied substitutions in PDE4B gene in the group of patients with panic disorder (PD) and the control group (Cont) and the subgroups." (PMID 31663033, 2019). "We estimated the frequencies of three SNPs in the PDE4B gene in a group of patients with panic disorder and a control group." (PMID 31663033, 2019). "The goal of our study was to evaluate the role of 3 SNPs in the PDE4B gene in the development of panic disorder." (PMID 31663033, 2019). "The frequencies of genotypes of the studied substitutions in PDE4B gene in the group of patients with panic disorder (PD) and the control group (Cont) as well as the subgroups." (PMID 31663033, 2019).
Parkinson disease (2 papers, 2021). A progressive degenerative disorder of the central nervous system characterized by loss of dopamine producing neurons in the substantia nigra and the presence of Lewy bodies in the substantia nigra and locus coeruleus. "It sponges microRNA-124-3p to up-regulate phosphodiesterase 4B (PDE4B) and accelerate the progression of Parkinson’s disease." (PMID 34151707, 2021).
psychosis (2 papers, 2015 to 2017). "The ZNF804A influences the expression of three genes involved directly in dopaminergic transmission (i.e. DRD2 and COMT) and cAMP signalling (i.e. PDE4B), two pathways thought to underlie many of the symptoms of psychosis." (PMID 28931092, 2017).
pulmonary hypertension (2 papers, 2023 to 2025). Increased pressure within the pulmonary circulation due to lung or heart disorder. "Using integrated bioinformatics analysis and experimental validation, we found that PDE4B expression was significantly elevated in both cell and animal models of OSA combined with pulmonary hypertension." (PMID 41243803, 2025). "Furthermore, PDE4B was shown to regulate the phosphorylation and nuclear translocation of FUS, which binds to the angiotensinogen (AGT) promoter and enhances AGT expression, thereby promoting pulmonary hypertension." (PMID 41243803, 2025).
Sepsis (2 papers, 2017 to 2024). Sepsis is defined as life-threatening organ dysfunction caused by a dysregulated host response to infection. "In a model of LPS-induced sepsis, only PDE4B-deficient mice displayed an increased circulating IL-1Ra, suggesting a protective role of PDE4B inactivation in vivo." (PMID 28383060, 2017). "However, there is evidence from mouse and rat models that phosphodiesterase 4B knockout prevents skeletal muscle atrophy resulting from denervation, limb immobilization, sepsis, or cancer." (PMID 38473107, 2024). "In summary, our data demonstrate that inhibition of PDE4B, one of the three PDE4 isoforms expressed in macrophages, upregulates anti-inflammatory cytokine IL-1Ra production in endotoxin-stimulated macrophages in vitro and sepsis in vivo." (PMID 28383060, 2017).
stress-related disorder (2 papers, 2021 to 2024). Stress-related disorders are mental health disorders that are a result of an atypical response to both short and long-term anxiety due to physical, mental, or emotional stress. "Based on GWAS data, PDE4B-selective inhibitors have been suggested as potential treatments for stress-related disorders." (PMID 39256048, 2024). "The lead SNPs for stress-related disorders and addiction risk, and the site of DNA methylation (cg14227435) that correlates with PDE4B expression and re-experiencing symptom severity in PTSD patients, are all located in PDE4B intron 3, thus implicating the long forms over the short forms." (PMID 39256048, 2024).
type 2 diabetes (2 papers, 2020 to 2021). "Specifically, the hyperinsulinemia that occurs with type 2 diabetes is associated with increased PDE4B content which thereby decreases cAMP and attenuates β-adrenergic signaling." (PMID 32817622, 2020).
acute kidney injury (1 paper, 2021). Sudden and sustained deterioration of the kidney function characterized by decreased glomerular filtration rate, increased serum creatinine or oliguria. "RT-qPCR validated miRNA and mRNAs included IGFBP2 (respiratory system); MMP9 and PDE4B (nervous system); PPARG (cardiovascular system); AKR1B1, ANXA1, and LNC2/NGAL (acute kidney injury); GFER/ALR (liver); and miR-30c-3p (coagulopathy)." (PMID 34573990, 2021).
acute lymphoblastic leukemia (1 paper, 2017). Leukemia with an acute onset, characterized by the presence of lymphoblasts in the bone marrow and the peripheral blood. "Taken together, our results suggest that the association of rs12142375 with acute lymphoblastic leukemia risk might be due to a direct regulatory role of rs12142375 in PDE4B gene expression." (PMID 29061142, 2017).
adenoma (1 paper, 2018). A neoplasm arising from the epithelium. "Including Pde4b, we have found 89 triply conserved genes with differential levels of transcripts– 75 enhanced and 14 diminished in adenomas and have identified common functional categories associated with this conservation." (PMID 30188895, 2018). "This study investigates by mutational analysis in the mouse whether PDE4B, the product of one of the triply conserved molecular transcriptome signals detected in ApcMin/+ adenomas and in the adjacent normal colonic epithelium, acts positively or negatively on adenomagenesis." (PMID 30188895, 2018). "The quantitative analysis of Pde4b transcripts by realtime PCR showed levels in the ApcMin/+ adenoma enhanced by 3.3-fold over those in the normal colonic epithelium of wildtype and tumor-free ApcMin/+ mice." (PMID 30188895, 2018). "A significant effect of the Pde4b genotype was observed on the number of adenomas in the colon of the ApcMin/+ mouse." (PMID 30188895, 2018). "Test of effect of the Pde4b genotype on the number of adenomas in the colon of ApcMin/+ mice over a series of backcross-intercross generations." (PMID 30188895, 2018). "Thus, it is plausible that the increase of Pde4b transcript in the ApcMin/+ adenomas and surrounding mucosa is secondary to active WNT signaling in the setting of loss of APC." (PMID 30188895, 2018). "Adenoma counts in the small intestine varied extensively for each Pde4b genotype; these differences were not significantly correlated with differences in the Pde4b genotype." (PMID 30188895, 2018).
adrenocortical tumors (1 paper, 2020). "In the present work, when the transcriptome analysis was accessed, a decrease of PDE2A, PDE5A, and PDE8A expression and a significant overexpression of PDE4B and PDE8B was observed in adrenocortical tumors, compared to normal adrenal tissue." (PMID 32098292, 2020).
age-related macular degeneration (1 paper, 2024). Age-related loss of vision in the central portion of the retina (macula), secondary to retinal degeneration. "The focus on PDE4B and PDE6H in relation to ocular diseases has intensified, with research indicating PDE4B’s dysregulation in conditions such as glaucoma, diabetic retinopathy, and age-related macular degeneration (AMD), positing it as a promising therapeutic target." (PMID 38605967, 2024).
alcohol use disorder (1 paper, 2024). "Furthermore, genetic variants in PDE4B have been associated with substance use disorders, including alcohol use disorder." (PMID 39285225, 2024). "Taken together, the results suggest that PET imaging of PDE4B in individuals with alcohol use disorder (AUD) should be considered in conjunction with ongoing trials of PDE4 inhibitors to treat alcohol withdrawal and reduce alcohol consumption." (PMID 39285225, 2024).
autoimmune disease (1 paper, 2021). A disorder resulting from loss of function or tissue destruction of an organ or multiple organs, arising from humoral or cellular immune responses of the individual to their own tissue constituents. "In contrast, young HSC human compartment was found with important expression of PDE4B a molecule implication in immune activation and potentially targetable by inhibitors such as Roflumilast used to correct inflammatory or autoimmune diseases." (PMID 34294125, 2021).
autoimmune hepatitis (1 paper, 2021). Hepatitis caused by autoantibodies. "This study aimed to assess the efficacy and explore the mechanisms of action of a potent phosphodiesterase (PDE)7A and a moderate PDE4B inhibitor GRMS-55 in a mouse model of autoimmune hepatitis (AIH)." (PMID 33919375, 2021).